EGFR (epidermal growth factor receptor)
Diseases named in the same sentence as EGFR in open-access papers (continued):
Sharing a sentence is not in itself a finding about the gene and the disease.
tumor (continued). "Further analysis encompassing single and double mutant constructs will help to clarify the role of these alterations on EGFR function and in tumour genesis." (PMID 21575252, 2011). "Our own studies have shed light on the expression and cellular localization of EGFR and E-cad in both tumor specimens and SCCHN cell lines." (PMID 21939503, 2011). "We also examined inhibition of target activity by measuring EGFR and ErbB2 phosphorylation levels in tumor extracts at indicated times after a single administration of AST1306." (PMID 21789172, 2011). "Antibodies and small molecule inhibitors have been developed impairing EGFR tyrosine kinase activity in various tumor types." (PMID 22140428, 2011). "Treatment with EGFR monoclonal antibodies was initially based on EGFR over-expression, assessed by immunohistochemistry (IHC) on formalin-fixed paraffin-embedded tumour specimens." (PMID 24212785, 2011). "Among the 160 samples, one primary tumor and seven metastases were identified with KRAS mutations and 21 primary tumors and 26 metastases were found to have EGFR mutations." (PMID 21414214, 2011). "The positive rate of EGFR protein in NSCLC tumor cells was 46%, which was significantly higher than its expression in normal lung (p = 0.0234) and paracancerous tissues (p = 0.020)." (PMID 21385353, 2011). "This approach was based on the knowledge that genes with evident DNE, such as EGFR and IDH1, represent nearly 100% of single heterozygous mutations in tumour specimens and cell lines." (PMID 21668955, 2011). "Of note, a steeper correlation between HAS3 and EGFR levels was found in the subgroup of T = 1 tumours, which possibly suggests a stronger dependence of this early tumour stage on EGF stimulated HAS3 expression." (PMID 21429221, 2011). "Ligand binding and EGFR activation triggers intracellular signalling pathways stimulating cell proliferation, motility, and survival—key processes in tumour growth and dissemination." (PMID 21386996, 2011). "The epidermal growth factor receptor (EGFR) is a well-established target for anticancer therapy because it is expressed or overexpressed in a variety of tumours, including non-small cell lung cancer (NSCLC)." (PMID 21915126, 2011). "A prominent example is the gene locus of the epidermal growth factor receptor (EGFR), which is a key player in tumor biology and an important target for individualized cancer therapy." (PMID 22140428, 2011). "Epidermal growth factor receptor (EGFR)-targeted therapies have been extensively evaluated in the clinic, and several EGFR-targeting products have been registered worldwide for the treatment of different tumor localizations." (PMID 24212794, 2011). "In turn, EGFR expression appears to play a potentially important role in modulation of tumor sensitivity to either chemotherapy or radiotherapy." (PMID 24212772, 2011). "Increased ligand-induced EGFR activation is a frequent driving force in carcinoma progression, and in many human tumours, excessive shedding of one or more EGFR-ligands appears to be a key contributing factor." (PMID 21386996, 2011). "This treatment approach looks appealing for further dedicated trials in EGFR promoter methylated tumours." (PMID 21559018, 2011). "Moreover, EGFR signaling could change in minutes order so it is crucial to monitor the dynamics of signal transduction to understand the intrinsic biological entity of tumor growth, in addition to the representative gene mutation status." (PMID 21554739, 2011). "EGFR gene copy number gain was detected in 14% (19/140) of tumours and in 12 of them was present only in 11–20% of cells." (PMID 21407808, 2011). "Erbitux (Cetuximab), a chimeric human-murine monoclonal antibody, competitively binds to the extracellular domain of EGFR, inhibits dimerization and reduces cell proliferation, preventing metastasis and further tumor growth." (PMID 24212824, 2011).
tumor (continued). "In particular, two patients with EGFR hypermethylation in the primary tumour showed unmethylated EGFR in metastasis and three metastases showing EGFR promoter hypermethylation derived from unmethylated EGFR primary tumours." (PMID 21559018, 2011). "The majority of tumours revealed EGFR low level copy number gain (56%), while high level copy number gain was less frequent (19%), and amplification was rare (3%)." (PMID 22152101, 2011). "In summary, ERBB2 and EGFR are transmembrane tyrosine kinases that can promote tumorigenesis and tumor progression." (PMID 21689422, 2011). "Although several combinations of EGFR inhibitors with chemotherapy demonstrate inhibition of tumor-induced angiogenesis, tumor cell apoptosis and regression in xenograft models, these benefits remain to be confirmed." (PMID 24212772, 2011). "Our finding is the first report showing curcumin is able to exhibit the prominent activity which enhances anti-tumor abilities of gefitinib in vitro and in vivo by modulating EGFR stability." (PMID 21858220, 2011). "Mouse xenograft tumor growth was significantly inhibited by cetuximab and both cetuximab-treated and -untreated xenograft specimens exhibited phosphorylations of the EGFR pathway proteins." (PMID 21554739, 2011). "C225-NP exhibited higher efficiency in induction of cell killing in comparison with the same amount of free C225 antibody in tumor cells with different levels of EGFR expression." (PMID 22087216, 2011). "In advanced tumours, EGFR, ERBB2 and ERBB3 upregulation is common and there is a relationship between expression of ERBB2 and ERBB3 but not the NRG1 ligand." (PMID 21364580, 2011). "This approach to establish GBM xenograft is the only means that has been shown to preserve tumor EGFR overexpression status and invasive growth pattern when compared with the established cell lines." (PMID 21314332, 2011). "This correlation suggests that EGFR over-expression on the tumor cells clearly induces T cell responses in the periphery." (PMID 21970318, 2011). "Of particular interest to the therapeutic treatment of HNSCC, EGFRvIII expression decreases the proliferative response of EGFR expressing tumor cells to cetuximab treatment relative to vector control cells." (PMID 21776391, 2011). "The Identification of additional molecular markers predictive of clinical benefit with EGFR TKIs in wild-type tumours would have therapeutic and economic implications for NSCLC patients." (PMID 22095222, 2011). "EGFRvIII remains an interesting tumor-specific target worthy of further exploration as a prognostic or predictive marker of response to EGFR inhibitor therapy in SCCHN." (PMID 21352589, 2011). "A further possible limiting factor is represented by the proportion of patients with a concordant EGFR methylation status between primary tumour and metastases (76%)." (PMID 21559018, 2011). "The preservation of tumor EGFR overexpression status as well as tumor invasiveness in the orthotopic setting will give the opportunity to assess the efficacy of developing novel therapeutic approaches for human GBM." (PMID 21314332, 2011). "Patients with tumours expressing high amounts of the EGFR had an improved response to treatment with erlotinib and the presence of specific mutations around the ATP binding domain of the receptor was found to increase the response to gefitinib treatment." (PMID 22095231, 2011). "We have investigated the affinity and kinetics of 125I-EGF binding to EGFR in four human tumor cell lines, each using four culturing conditions, in real time by use of LigandTracer®." (PMID 21304974, 2011). "We analyzed the genetic status of the epidermal growth factor receptor gene in a series of specimens obtained from various tumor-containing lesions throughout the therapeutic period." (PMID 22108465, 2011). "The tyrosine kinase inhibitor gefitinib inhibits growth in some tumor types by targeting the epidermal growth factor receptor (EGFR)." (PMID 21931838, 2011).
tumor (continued). "Misclassification of KRAS mutation status has important clinical consequences because KRAS testing of tumor tissue is often used as the sole determinant for selection of anti-EGFR therapy." (PMID 21110880, 2010). "The expressions of VEGF-C mRNA and EGFR mRNA in tumor tissues and lymph node tissues were significantly correlated (r=0.834, P < 0.001; r=0.817, P < 0.001)." (PMID 21159248, 2010). "Normal mammary glands (Group A) showed the lowest level of EGFR mRNA expression, while mammary glands from tumor-bearing mice (Group B) showed the highest expression level." (PMID 20092659, 2010). "EGFR, one of the important markers for glioblastioma multiforme, was strongly expressed on membrane and in cytoplasm of tumor cells." (PMID 20587035, 2010). "EGFR and its family members play a variety of roles in oncogenesis and tumor progression in different cancer and cell types." (PMID 20037743, 2010). "For EGFR, we observed a band around 170 kDa in extracts from tumours 4 and 7 that corresponds to the normal position of EGFR." (PMID 21170331, 2010). "For TGFA/EGFR, a significant direct and inverse correlation was observed in normal and tumor samples, respectively." (PMID 20877637, 2010). "The data here showed that TGFαL3 is capable of targeting superantigen to tumours and exerting an inhibitory effect on tumour growth, which enables TGFαL3SEAD227A to be an attractive candidate for the immunotherapy of EGFR-expressing tumours." (PMID 21176167, 2010). "The high levels of VEGF-A and EGFR expression in SBA provide a rationale for the exploration of therapies targeting these oncogenic pathways in this rare tumour type." (PMID 19935793, 2010). "Activating mutations in the tyrosine kinase domain, involving mainly exons 19 and 21, play an important role in lung oncogenesis and tumor progression and are related to the clinical efficacy of EGFR TKIs such as gefitinib or erlotinib." (PMID 21167064, 2010). "The relationship of salivary levels and EGFR and Her-2 immunoexpression in tumor samples with clinicopathological features was analyzed." (PMID 20429940, 2010). "The CISH study demonstrated a high-EGFR gene copy number, with balanced chromosome 7 polysomy, in 8 out of 11 high-grade MECs (72.7%), whereas 27 low-grade and 15 intermediate-grade tumours had a normal EGFR gene copy number (P<0.001)." (PMID 20664595, 2010). "Nevertheless, the affinity of TGFα3L with EGFR is weaker than that of full length TGFα, which raised a concern for its ability to bring superantigen to the tumour in vivo." (PMID 21176167, 2010). "Nevertheless, the results obtained with tumours arboring different copy numbers of the EGFR, SEC61G, LANCL2 and VOOP1 genes allow us to establish that mRNA over-expression parallels the level of amplification." (PMID 21170331, 2010). "The immunoexpression of EGFR and Her-2 in tumor samples was evaluated and correlated with the salivary levels of these proteins and the clinicopathological features of the tumors." (PMID 20429940, 2010). "Linear correlation analysis revealed there was a correlation of the expression of EGFR protein between peripheral blood and tumor tissue (P=0.016, R2=0.83)." (PMID 21159244, 2010). "We previously reported on the expression of tumor antigens EGFR and Her-2 in our large well-documented cohort of representative EOC, using tissue microarray." (PMID 20885926, 2010). "In the present study, these two rabbit mAbs were used to assess EGFR mutations in five NSCLC cell lines and in tumor biopsies from 78 stage IV NSCLC patients." (PMID 21167064, 2010). "Recent studies on laryngeal, esophageal, and uterine cervical carcinoma also found that the EGFR status of the primary tumor was retained in the metastases." (PMID 20096104, 2010). "One of the main subjects of debate is the relevance of KRAS genotyping on primary tumours, whereas anti-EGFR mAbs are used to treat a metastatic disease." (PMID 21139621, 2010).
tumor (continued). "The results obtained by Qian and coworkers suggest the highly specific recognition and detection of human cancer cells, as well as active targeting of EGFR-positive tumor xenografts in animal models can be made using SERS." (PMID 21180459, 2010). "Many kinds of tumour cells express multiple EGFR members, which interact to form an array of homodimers and heterodimers." (PMID 20664599, 2010). "The European Medicines Agency has also recognised these findings, and indeed also restricts the use of anti-EGFR antibody therapy only to CRC patients with wild-type (wt) KRAS tumours." (PMID 20959826, 2010). "Combining lovastatin with gefitinib, a potent EGFR inhibitor, induced synergistic cytotoxicity in a variety of tumor derived cell lines." (PMID 20838437, 2010). "As shown in this paper, TGFαL3SEAD227A can inhibit tumour growth in a EGFR-dependent way, implying that the affinity of TGFαL3 is sufficient for targeting the superantigen to the tumour." (PMID 21176167, 2010). "We found significant correlation of EGFR expression and tumor stage (P = 0.042), β-catenin and tumor size (P = 0.025) and stage (P = 0.031), and of EGFR expression and β-catenin cytoplasmic/nuclear expression and cyclin-D1 immunoactivity (P < 0.0001 for both)." (PMID 20302655, 2010). "IHC correctly identified del 19 in the H1650 and PC9 cell lines, L858R in H1975, and wild-type EGFR in H460 and A549, as well as wild-type EGFR in tumor samples from 22 patients." (PMID 21167064, 2010). "Among these genes, the SEC61G gene was co-amplified with EGFR in 5 tumours and the VSTM2A gene in 4 of them." (PMID 21170331, 2010). "According to the criterion that samples with more than 10% of tumor cells showing membranous staining at levels 2+ and 3+ should be considered to be EGFR IHC-positive, 91 cases were IHC-positive and 42 cases were negative." (PMID 20637128, 2010). "PDGF and VEGF are autocrine growth factors in MM and the epidermal growth factor receptor (EGFR) appears highly expressed in this tumor." (PMID 24281081, 2010). "Of these genes, the imprinted gene decorin and the oncogene EGFR were down-regulated in tumor tissues as compared to normal mammary gland tissues, and the oncogene cyclin D1 was up-regulated in tumor tissues." (PMID 20092659, 2010). "The enhancement of RANKL expression was blocked by gefitinib treatment, thus linking the tumour-inhibitory effect of EGFR inhibitors to RANKL-mediated osteoclast activation." (PMID 20010942, 2010). "Tumours overexpressing EGFR (P=0.0002) or phospho-EGFR (P=0.015) showed increased Ki-67, but not caspase-3 expression." (PMID 19997103, 2010). "Very little is known about the link between cannabinoid and EGFR signalling in cancer, and nothing is known in this respect in human tumour tissue." (PMID 21203460, 2010). "In a univariate analysis, patient tumours expressing phospho-EGFR had similar DFS and OS survival rates as did tumours lacking phospho-EGFR." (PMID 19997103, 2010). "Studies indicate that prostaglandin E2 (PGE2), a product of cyclooxygenase-2 (Cox-2) activity, promotes tumor growth by activating EGFR or β-catenin." (PMID 20828404, 2010). "Human transforming growth factor alpha (hTGFα) is a native ligand co-overexpressed with its receptor EGFR in many human tumours." (PMID 21176167, 2010). "One of them is that KRAS mutations should be examined in the clinical trials on the effect of EGFR blockade in this tumor type." (PMID 20565817, 2010). "Epidermal growth factor receptor (EGFR) is a member of the erbB family of tyrosine kinases (TK) receptor proteins, that play an important role in tumor progression." (PMID 20843314, 2010). "In the era of targeted therapy for cancer, molecular diagnosis of particular genetic markers in tumours enables a more individualised treatment of patients, as was recently shown for KRAS mutation status and response rate to anti-EGFR therapy in CRC." (PMID 20959826, 2010).
tumor (continued). "Both the analyses identified the coordinated expression of the TGFA/EGFR L/R pair in tumor samples when compared with normal tissue." (PMID 20877637, 2010). "We first focussed on these simple situations, in which the amplicons range from 0.7 to 2.1 megabases depending on the tumour, and all include the EGFR gene." (PMID 21170331, 2010). "Recent studies show that NGX6 gene can reduce tumor formation and tumor size in nude mice by down-regulating the EGFR/K-ras/JNK/c-Jun/cyclin D1 and Wnt/beta-catenin/TCF/LEF signal pathways." (PMID 20423473, 2010). "Gefitinib, a tyrosine kinase (TK) inhibitor of epidermal growth factor receptor (EGFR), displays anti-tumor activity." (PMID 20843324, 2010). "Others studied the in vitro synergistic anti-tumour effects after combined EKI-785 (EGFR inhibitor) with rapamycin on glioma cell lines." (PMID 20515495, 2010). "Phospho-EGFR expression was detected in 157 of 388 (40%) tumours, whereas EGFR was found in 214 of 361 (59%)." (PMID 19997103, 2010). "The total number of EGFR-positive cases with either complete or incomplete circumferential immunostaining of the tumour cell membranes was 19% (27 of 140 cases)." (PMID 20502457, 2010). "Fusion protein TGFalphaL3SEAD227A can promote splenocyte proliferation to a level comparable to recombinant SEA (rSEA) and bind to EGFR-expressing tumour cells in an EGFR-dependent way." (PMID 21176167, 2010). "The epidermal growth factor receptor (EGFR) pathway is a well-known molecular target in several human tumours." (PMID 20683448, 2010). "EGFR intensity was also borderline significance for OS (HR: 1.15 (0.98, 1.34), P=0.086) in a model that included age, tumour stage, histological grade, and MMR status." (PMID 19997103, 2010). "A preclinical evaluation of the combination of ionising radiation and 4 h after the last radiation dose showed that a vascular disrupting agent, ZD6126, combined with the anti-EGFR Gefitinib did enhance in vivo tumour growth delay in NSCLC models." (PMID 20628392, 2010). "In cancer tissues, EGFR expression correlated with the presence of nuclear β-catenin, and nuclear β-catenin correlated with the tumor malignancy index." (PMID 20302655, 2010). "In tumor cell lines and xenograft models, lapatinib has inhibited EGFR and p-ErbB2, p-Erk1/2, p-AKT, and cyclin D, and this effect was dose and time dependent." (PMID 21050422, 2010). "Chemosensitization by EGFR inhibition was demonstrated in early studies using blocking antibodies in combination with cisplatin or doxorubicin in human tumor xenografts." (PMID 20064265, 2010). "The expressions of VEGF-C mRNA and EGFR mRNA in tumor tissues and lymph node tissues were significantly higher than those in control group (P < 0.05)." (PMID 21159248, 2010). "Using EGFR-specific siRNAs or EGFR-targeted drugs was proposed as a strategy to counter this adaptation and induce tumor regression." (PMID 20126311, 2010). "EGFR activation appears to promote tumor growth and progression by controlling transcription, cell-cycle progression, apoptosis and differentiation." (PMID 20398370, 2010). "The expression of EGFR was analyzed by real-time RT-PCR in 46 NSCLC tumor tissues and by ELISA in peripheral blood, compared with 10 patients with benign pulmonary diseases as control." (PMID 21159244, 2010). "Consistent with the literature 86% (24/28 cases) of investigated tumor samples showed an expression of EGFR on protein level." (PMID 20196851, 2010). "Numerous studies reported on the prognostic value of overexpression of EGFR in many tumour types including HNSCC." (PMID 20502457, 2010). "It was shown that treatment of SCLC cell lines with a monoclonal EGFR antibody reduced invasiveness of tumour cells in vitro." (PMID 20683448, 2010). "One hundred % of metastases of hormone-refractory prostate cancers express EGFR, suggesting that this receptor is a major transduction pathway for tumor growth." (PMID 27713352, 2010).